AGR2 (anterior gradient 2, protein disulphide isomerase family member)
Diseases named in the same sentence as AGR2 in open-access papers (continued):
Sharing a sentence is not in itself a finding about the gene and the disease.
tumor (continued). "Collectively, these findings imply that multiple splice variants of AGR2 may be present in the same cancer cell lines or in the same cancer patients, and that ER-resident and secreted AGR2 may simultaneously be involved in tumor development and chemotherapeutic sensitivity." (PMID 33413231, 2021). "Our finding indicates that secretory AGR2 alters fibroblasts elongation, migration, and organization suggesting the secretory AGR2 as a potential molecular target that might be responsible to alter fibroblasts infiltration to support tumor growth." (PMID 31710263, 2019). "Thus, tools that enable assessment of eAGR2 levels such as anti-AGR2 DNA aptamers or peptides may provide important clinical readouts of tumor burden, response to therapy, and/or patient prognosis." (PMID 29937991, 2018). "Thus, the prognostic value of AGR2 in tumours remains elusive and needs to be clarified." (PMID 29138453, 2017). "Their data from 68 patients support our findings as AGR2 expression reported in GEO showed a significantly higher average expression levels in grade (II+) tumors/or tumors that reoccurred compared to grade I tumours (grade I: 104.285, grade II+/reoccurred: 988.182, T test P 0.021)." (PMID 28736504, 2017). "Additionally, cancer-secreted AGR2 could facilitate tumor spread by inducing PCD in endothelial cells of the vessel lining, making blood vessels leaky to allow access by the cancer cells." (PMID 27283903, 2016). "To determine whether AGR2 is required for tumor progression in vivo, we then evaluated the in vivo tumorigenic potential of Sh-ctl and Sh-AGR2 cells using two different adenocarcinoma cell lines (A549 and H1838), following tail vein injection in immunodeficient mice." (PMID 27240165, 2016). "Importantly, AGR2 protein concentrations are found to be significantly elevated in serum and/or plasma samples of ovarian, lung and prostate cancer patients compared to healthy controls proposing AGR2 as a putative cancer serum biomarker in these tumour entities." (PMID 25875093, 2015). "AGR2 is the prooncogenic protein that could be used as a tumor biomarker." (PMID 25243088, 2014). "The function of AGR2 in human tissue is largely unknown, but overexpression of AGR2 has been reported in several cancers, including breast, prostate, lung and pancreas and in circulating tumor cells." (PMID 20550709, 2010). "However, upon transfection of an expression vector for AGR2 into parental Rama 37 cells and their transplantation into syngeneic rats, the primary tumours appear on average with an increased latency compared to that for S100A4-transfected, osteopontin-transfected or the parental Rama 37 cells." (PMID 16598187, 2006). "It is tempting to speculate that a similar effect of AGR2 in human tumours may account for the late effect on patient outcome found in the ERα-positive group in this study; the survival curves do not begin to separate until approximately 40 months and become significant only at 6 years." (PMID 16598187, 2006). "AGR2 represents a critical effector of ERCYS and highlights how ER-derived proteins can be repurposed in the cytosol to support tumor progression by spatial remodeling." (PMID 40839310, 2025). "Here, the tumor cells elevate expression of immune signaling MHC II molecules (CD74, HLA-DRB1, HLA-DPA1) and immune-regulating secretory proteins (REG4, AGR2, AGR3), with AGR2 and REG4 specifically upregulated in RCRC." (PMID 41450739, 2025). "They express proteins like AGR2 to potentiate VEGF and FGF2 signaling, and REG4 to intensify tumor invasion." (PMID 41450739, 2025). "And 4HNE and ki67 staining proved that AGR2 KO and IKE treatment induced ferroptosis and inhibited tumor proliferation, all of which were reversed by the ferroptosis inhibitor Lip-1." (PMID 41326375, 2025). "BL tumor cells exhibited elevated expression of MGP (matrix Gla protein), AZGP1 (alpha-2-glycoprotein 1), AGR2 (anterior gradient protein 2), TFF3 (trefoil factor 3), and FGFR1 compared to EP and LP cells." (PMID 39955556, 2025).
tumor (continued). "Anterior gradient homology protein 2 (AGR2) has emerged as a significant prognostic indicator for multiple cancers, while anti-cancer 1 (KAI1), recognized as a tumor metastasis suppressor gene, plays a critical role in cancer progression." (PMID 41239615, 2025). "By in vivo results, AGR2 KO or IKE treatment significantly inhibited tumor growth, and the combination of AGR2 KO and IKE treatment significantly suppressed tumor growth." (PMID 41326375, 2025). "Meanwhile, subcutaneous tumor model and lung metastasis model were used to validate the functional role of the HNF4A-AS1/PCBP2/AGR2 axis in vivo." (PMID 39430249, 2024). "Among the 991 BC tumor samples, GATA3 had the highest frequency of somatic SNVs, accounting for 13%; followed by FOXA1, accounting for 3%; AGR2, CA12, CEP55, CDC20, TBC1D9, and MELK had very few somatic SNVs." (PMID 39440050, 2024). "We suggest that the correlation between AGR2 and XBP1 needs to be further demonstrated in more clinical specimens in the future (Normal: lanes 1–9, Tumor: lanes 1–5)." (PMID 36899352, 2023). "The balance between AGR2 and ZEB1 is suggested to govern the aggressiveness and invasive phenotype of tumor cells." (PMID 36329620, 2023). "There was also significant positive correlation between the expression levels of AGR2 and FOXA1 in both tumor tissues (r = 0.441, P < 0.001) and adjacent tissues (r = 0.567, P < 0.001)." (PMID 37568077, 2023). "In our study, the expression levels of AGR2 and FOXA1 in tumor tissues were significantly higher than that in adjacent tissues and there was a positive correlation between them." (PMID 37568077, 2023). "Univariate analysis showed that male sex (P = 0.009), tumor size (P = 0.045), CLIP score (P = 0.002), BCLC stage (P < 0.001), AJCC stage (P < 0.001), and high AGR2 level (P = 0.003) were significant predictors of worse RFS." (PMID 36899352, 2023). "Reduces tumor weight, increases the levels of IFN-γ, TNF-α, GZMB and the expression of CLCA3, TFF3, AGR2, Zg16, Pla2g10, Guca2a." (PMID 35548468, 2022). "Tumor cells in LNs showed cytoplasmic expression of PSA, PSCA, and AGR2; membrane and cytoplasmic expression of PSMA and EpCAM; and nuclear expression of NKX3-1." (PMID 36185585, 2022). "Anterior gradient protein 2 homolog (AGR2), an endoplasmic reticulum protein, is secreted in the tumor microenvironment." (PMID 35055132, 2022). "Since AGR2 and AGR3 expressions were highly correlated in all the TCGA tumour types studied as well as in the CCLE collection, we focused our interest on AGR2 and simply indicated original features concerning AGR3." (PMID 35857928, 2022). "Thus, AGR2 may facilitate tumor resistance against proteotoxic stress, preventing tumor cell death." (PMID 35804819, 2022). "Indeed, concomitant or opposed of AGR2 and AGR3 expression in EOC could determine tumour evolution in a way that would promote its growth and aggressiveness, thus associating the differential expression of AGR2 and AGR3 to tumour outcomes." (PMID 34452625, 2021). "While further studies are needed to determine if AGR2 functions as a bona fide PDI, accumulating evidence indicates that AGR2 plays roles in tumor development by stimulating the proliferation and promoting the metastasis of cancer cells." (PMID 33717413, 2021). "Anterior gradient protein 2 (AGR2) maintains the epithelial phenotype and blocks the induction of EMT, thus playing an undeniable role in tumor progression." (PMID 32570918, 2020). "Based on these data, we can conclude that alteration of the balance between AGR2 and ZEB1 in favor of ZEB1 leads to the acquisition of an aggressive and more invasive phenotype of tumor cells." (PMID 32570918, 2020).
tumor (continued). "We were therefore able to analyze the expression of NANOG, SOX2, OCT4, AGR2, KLF4, and NOTCH1 in only 11 tumor samples and corresponding TANT (22 FFPE tissue samples)." (PMID 32733958, 2020). "AREG was also upregulated in OPA, and as for AGR2, IHC demonstrated positive labeling for AREG in OPA tumor cells from both natural and experimentally induced disease." (PMID 31434729, 2019). "Through a network-based analysis, the intracellular AGR2 protein was identified to accompany the PAUF protein, which is involved in tumor metastasis, in cervical cancer cells." (PMID 31247903, 2019). "We utilized two AGR2 antibodies, P3A5 and P1G4, for in vivo tumor localization and tumor growth inhibition." (PMID 31303962, 2019). "All five of the proteins predicted to be upregulated in EAC compared with normal esophagus (SAMHD1, ARHGDIB, AGR2, HSPA5, EPCAM) showed higher expression in the tumor sections compared with squamous epithelium." (PMID 28336725, 2017). "Interestingly, soft-agar colony formation (used as indicator of malignant transformation) significantly reduced upon AGR2 silencing in adenocarcinoma cell lines, thereby indicating that AGR2 may favor tumor progression by increasing anchorage-independent growth." (PMID 27240165, 2016). "In adenocarcinoma organoids (H23), we found ~20% of eAGR2 and ~80% of iAGR2, while in non-tumor organoids (HBEC-EV), AGR2 protein was exclusively intracellular." (PMID 27240165, 2016). "In contrast to the AGR2-AXXA mutant, AGR2-SXXS mutant restored the formation of AGR2-depleted tumor organoids." (PMID 27240165, 2016). "For the first time, we demonstrated the increase of AGR2 protein in HNSCC in correlation with aggressive phenotype HNSCC, as indicated by high protein expression, high pathological grade, large tumor burden, positive lymph node status, and recurrence." (PMID 25871396, 2015). "Knockdown of AGR2 expression in SNU-478 cells suppressed certain tumor phenotypes, including growth, anchorage-independent growth, and in vivo tumor xenograft formation." (PMID 25367337, 2014). "P08-029pre, which came from a small tumor volume of 0.6 cc, showed marginal increase (2- to 3-fold above background) for these genes except for AMACR: AGR2 = 0.16, AMACR = 0.32, CRISP3 = 0.78, ERG = 0.28, HPN = 0.12, PCA3 = 0.19." (PMID 23029164, 2012). "Our findings indicate that the quantitative molecular assessment of AGR2 and LGR5 can serve as a surrogate marker of CTC and ISC-like circulating tumor cells in CRC patients." (PMID 22605983, 2012). "Cluster I consisted of genes upregulated in CC cells, which included tumor-related genes such as LGR4, AGR2, PCAF, TMEM97, FRAT2, EFNB2 and ZIC2." (PMID 21333016, 2011). "In turn, the relationships between AGR2 and other tumour variables reflected this strong association with ERα positivity; thus, staining for AGR2 is associated with tumours of lower grade but not with tumour size, nodal status or the presence of lymphovascular invasion." (PMID 16598187, 2006). "Staining for AGR2 was associated with poorer survival of patients with smaller tumours (T1 tumours n=117; log rank test, P=0.007; Wilcoxon test χ2=7.6, 1 d.f., P=0.006), but not with patients with larger tumours (T⩾2, n=94, log rank test, P=0.6; Wilcoxon test χ2=0.02, 1 d.f., P=0.9)." (PMID 16598187, 2006). "After normalization to anti-BSA levels, standardized ratios of anti-AGR2, anti-HAPLN1, anti-IGFBP5, and anti-TYMS were significantly higher in malignant and early-stage CMTs, suggesting selective amplification of tumor-specific immune responses despite global immune suppression." (PMID 41562247, 2026). "Consequently, miR-217 overexpression induced therapeutic effects such as reduced tumor burden in the liver and prolonged lifespan of mice transplanted with K562DR through a mechanism involving simultaneous downregulation of AGR2 and sensitization to Dasatinib." (PMID 40867591, 2025).
tumor (continued). "Notably, AGR2, which significantly influences the EGFR signalling axis and tumour pathogenesis, exhibited the highest increase in the expression level." (PMID 40038875, 2025). "In contrast, the lower region has extensive α-Sma, due to intermingled myCAFs, Yap/Taz, and Ki67, indicative of highly proliferative tumor cells, yet virtually no mucin, Ecad, Agr2, or p-Erk1/2 staining." (PMID 38672675, 2024). "Similarly, the gene expression of the predicted targets AGR2 and AHSG were also determined between normal and CRC tumour groups." (PMID 39348343, 2024). "Our study highlights the pro-tumor function of extracellular AGR2 (not cell surface-localized) and supports the use of agents that bind and neutralize AGR2 function." (PMID 39727484, 2024). "AGR2 can affect cell signaling and metabolism by upregulating the expression of CCAAT-enhancer-binding protein β and the transcription factor hypoxia-inducible factor 2α subunit, thereby promoting tumor development." (PMID 38277205, 2024). "Therefore, the comparisons of AGR2 and FOXA1 levels between tumor tissues and adjacent tissues were performed among 549 and 541 patients, respectively." (PMID 37568077, 2023). "AGR2 contributes to maintain epithelial cell phenotype, inhibits EMT induction, and enhances the rate of adhesion to plastic substratum, thus playing an undeniable role in tumor development and progression." (PMID 36329620, 2023). "AGR2 and STOX2 were previously identified as promoters of tumor progression." (PMID 36232621, 2022). "These variations are not recurrent and cannot be considered as oncogenic variations since the tumours and cell lines bearing these variations do not behave differently than the others in terms of AGR2/3 gene expression." (PMID 35857928, 2022). "Notably, AGR2 can directly bind to VEGF and fibroblast growth factor 2 (FGF2), thus leading to enhanced metastasis and tumor progression." (PMID 35055132, 2022). "The overall conclusion of these explorations of AGR2 and AGR3 genomic variations in tumours and cancer cell lines is that it is quite unlikely that they could behave as bona fide oncogenes or TSG." (PMID 35857928, 2022). "We observed that GATA4, AGR2, and PPARG were significantly underexpressed in tumor samples." (PMID 35069736, 2022). "As a consequence, the regulation of AGR2 activities and localizations (erAGR2, cAGR2 and eAGR2) in EOC might determine tumour evolution in a way that would promote its growth and aggressiveness." (PMID 34452625, 2021). "As a consequence, expression regulation of both AGR2 and AGR3 in EOC could determine tumour evolution in a way that would promote its growth and aggressiveness." (PMID 34452625, 2021). "The Cox proportional hazard regression model showed that the absence of AGR2 protein expression in the tumour was a strong predictor of poor disease-free survival (HR: 0.631; 95% confidence interval: 0.412–0.966; P = 0.034)." (PMID 34452625, 2021). "The results showed that the AGR2 overexpression had a negative effect on the overall survival (OS) and time to tumor progression (TTP) of patients with a solid tumor." (PMID 31247903, 2019). "A Cox proportional hazards regression model showed that the absence of AGR2 protein expression in the tumor was a strong predictor of poor DFS (HR: 0.631; 95% confidence interval: 0.412‐0.966; P = .034)." (PMID 29845750, 2018).
tumor (continued). "PTC and FTC tumours presented a group of common dysregulated proteins including SOD3, ISLR, biotinidase, polymerase I and transcript release factor (cavin-1), TFF3, alpha(B)-crystallin (CryAB), AGR2, tenascin and 14-3-3 gamma." (PMID 27025787, 2016). "The addition of DTT to the medium of AGR2-depleted H23 cells neither reversed the cell growth inhibition induced by AGR2 depletion nor restored the formation of tumor organoids." (PMID 27240165, 2016). "Although it has been only correlated that AGR2 may stimulate EMT, it is intriguing to find that eAGR2 in ECM is sufficient by itself, to induce EMT in non-tumor epithelial cells." (PMID 27240165, 2016). "To further assess the redox function of eAGR2 in such process, we treated tumor organoids depleted in AGR2 (H23-Sh-AGR2) with dithiothreitol (DTT) at a concentration of 5μM and no cell death was detected." (PMID 27240165, 2016). "The addition of AGR2 protein was enough to change the non-tumor organoids into tumor organoids and boosted their growth about ten-fold." (PMID 27240165, 2016). "Protein O-GlcNAcylation was examined in non-tumor organoids overexpressing AGR2 (HBEC-AGR2) or not (HBEC-EV) following eAGR2 immunoprecipitation." (PMID 27240165, 2016). "This is independent of iAGR2 since the reduced tumor organoids formation in AGR2-depleted cells can be restored by addition of exogenous eAGR2." (PMID 27240165, 2016). "No detectable tumor xenograft was formed in nude mice injected with AGR2-silenced SNU-478 cells, whereas AGR2-expressing SNU-478 cells formed palpable tumors." (PMID 25367337, 2014). "Unlike the results of the soft agar colony-forming assay, the AGR2 knockdown resulted in mixed responses among the KD clones and did not significantly inhibit invasion of the tumor cells." (PMID 25367337, 2014). "DNP induces AGR2 expression, and DNP-mediated AGR2 stimulates the production of CTS from endothelial cells, thereby stimulating the remodeling of ECM and accelerating tumor invasion and metastasis." (PMID 24717913, 2014). "Our findings indicate that the assessment of AGR2 and LGR5 in PB might reflect the presence of circulating tumor cells (CTC) and stem cell like CTC in CRC." (PMID 22605983, 2012). "Within the present study cohort, plasma concentrations of MDK and AGR2 were not significantly altered by tumor type or stage of disease." (PMID 20525245, 2010). "AGR2 expression was not predictive of tumor recurrence either as a continuous or dichotomized variable (P = 0.596 and P = 0.281)." (PMID 21144054, 2010). "Nevertheless, this average slower tumour growth does not hinder the ability of AGR2-transfected cells to form metastases, it merely delays it." (PMID 16598187, 2006). "Moreover, extracellular AGR2 promotes the conversion of non-tumor organoids to tumor organoids, enhancing growth of the organoids approximately ten-fold." (PMID 40867591, 2025). "Therefore, the expression of AGR2 was clear in all groups, but had no influence on the tumor heterogeneity or the anatomical forms analyzed in this study." (PMID 40941427, 2025). "Therefore, AGR2 expression was analyzed in more than 14,000 tumor tissue samples from 134 different tumor types and subtypes as well as 76 nonneoplastic tissue categories by immunohistochemistry (IHC) in a tissue microarray (TMA) format in this study." (PMID 39533806, 2024). "Notably, AGR2 encompasses an N-terminal signal sequence and can be secreted from both non-tumor and tumor cells into the extracellular milieu through the conventional secretory pathway." (PMID 38822246, 2024). "Moreover, extracellular AGR2 was observed to directly interact with and enhance the vascular endothelial growth factor (VEGF) and fibroblast growth factor 2 (FGF2), contributing to angiogenesis and tumor growth." (PMID 33413231, 2021). "AGR2 expression increased 2-fold in tumor tissues compared to normal tissues." (PMID 34632938, 2021).